CRP (C-reactive protein)
Diseases named in the same sentence as CRP in open-access papers (continued):
Sharing a sentence is not in itself a finding about the gene and the disease.
personality disorder (3 papers, 2021 to 2025). A diverse category of psychiatric disorders characterized by behavior that deviates markedly from the expectations of the individual's culture; this pattern of deviation is pervasive and inflexible and is stable over time. "The second study found that in a sample of 34-year-olds with and without personality disorders, retrospective reports of parental psychological control were positively correlated with IL-6 and CRP concentrations, independent of personality disorder diagnosis." (PMID 34347228, 2023).
placental abruption (3 papers, 2019 to 2023). Vaginal bleeding preceding the 20th week of gestation. "This retrospective case-control study revealed that placental abruption was associated with slightly but significantly increased CRP levels." (PMID 30970668, 2019). "The most important findings are the increased CRP serum levels in women with placental abruption compared to controls, which became evident in patients both with and without vaginal bleeding." (PMID 30970668, 2019). "The significantly increased CRP levels found for women with placental abruption, and the lack of a difference in CRP between bleeding and non-bleeding cases, seem in line with the theory of a chronic process being associated with placental abruption." (PMID 30970668, 2019). "The significantly increased CRP levels found for women with PA and the lack of a difference in CRP between bleeding and non-bleeding cases point toward a chronic process underlying placental abruption." (PMID 30970668, 2019). "In our data set, the increases in CRP levels observed in cases could be due to this slow development of a clinically recognizable status of placental abruption." (PMID 30970668, 2019). "Thus, CRP can be assumed to be an independent predictor for placental abruption." (PMID 30970668, 2019). "Thus, we aimed here to evaluate routine laboratory parameters, i.e., hemoglobin, leukocytes, thrombocytes, CRP, and fibrinogen, in women with and without placental abruption." (PMID 30970668, 2019). "As early as in the first trimester, C-reactive protein (CRP) levels, chlamydia pneumoniae-/trachomatis-specific immunoglobulins G and A, or CHSP60 antibody frequencies, are not altered in women with subsequent placental abruption." (PMID 30970668, 2019).
Pneumocystis jirovecii pneumonia (3 papers, 2018 to 2025). "Increasing CRP and LDH levels accompanied by dry cough raised the suspicion of pneumocystis pneumonia (PCP)." (PMID 35821079, 2022).
polycystic kidney disease (3 papers, 2017 to 2025). A usually autosomal dominant and less frequently autosomal recessive genetic disorder characterized by the presence of numerous cysts in the kidneys leading to end-stage renal failure. "This is reflected in the earlier observation of relatively low urine (THF+5αTHF)/THE in patients with polycystic kidney disease, as this subgroup also exhibited low CRP." (PMID 30358903, 2019).
polycythemia vera (3 papers, 2017 to 2023). "Emerging work highlights the fundamental contribution of systemic inflammation to MPN procoagulant state, as shown by the stepwise association of C-reactive protein levels and the thrombotic risk in both ET and Polycythemia Vera." (PMID 32425934, 2020).
postmenopausal osteoporosis (3 papers, 2019 to 2023). Metabolic disorder associated with fractures of the femoral neck, vertebrae, and distal forearm. "Such consideration is even more reasonable owing to PD-1 being significantly upregulated in PBMCs of patients suffering from postmenopausal osteoporosis, which represents an imbalance in the OC/OB activity ratio and further correlates with elevated C-reactive protein (CRP) levels." (PMID 36817431, 2023).
Protein-losing enteropathy (3 papers, 2021 to 2025). Abnormal loss of protein from the digestive tract related to excessive leakage of plasma proteins into the lumen of the gastrointestinal tract. "Since lipoproteins, C-reactive protein and paraoxonase-1 take part in inflammation, investigating their changes in dogs with protein-losing enteropathy secondary to chronic inflammatory enteropathy (iPLE) is crucial." (PMID 39518842, 2024).
protozoal infections (3 papers, 2019 to 2025). "Such an increase in CRP has been reported in travelers in tropics with protozoal infections." (PMID 31442248, 2019).
puerperal infection (3 papers, 2012 to 2023). An infection occurring in puerperium, the period of 6-8 weeks after giving birth. "For this reason, CRP can be used as a biomarker of bacterial infection and may be associated with the risk of puerperal infection (data not evaluated)." (PMID 36430023, 2022).
Pulmonary hemorrhage (3 papers, 2010 to 2025). Pulmonary hemorrhage is a bleeding within the lungs. "MPA is clinically characterized by a multisystemic disease such as RPGN, pulmonary hemorrhage, mononeuritis, and skin involvement, as well as other manifestations in conjunction with high levels of inflammatory activity such as high ESR or CRP." (PMID 20981310, 2010).
rapid eye movement sleep behavior disorder (3 papers, 2023 to 2024). "Moreover, the LMR and C-reactive protein (CRP) level may serve as useful predictors of patient prognosis in patients with PD combined with rapid eye movement sleep behavior disorder." (PMID 38322584, 2024).
Restrictive lung disease (3 papers, 2019 to 2024). "Increased levels of serum C-reactive protein (a marker of systemic inflammation) have been positively correlated with decreased lung function, obstructive and restrictive lung diseases, and visceral fat." (PMID 33407481, 2021).
retropharyngeal abscesses (3 papers, 2017 to 2023). "Furthermore, in retropharyngeal abscesses, CRP was higher (12.8 mg/dL vs. 6.85 mg/dL), emphasizing the systemic relevance of retropharyngeal abscesses." (PMID 37761467, 2023). "Our study shows that AST, ALT and CRP levels were significantly higher and WBC levels were significantly lower in IKD initially presenting as retropharyngeal abnormalities than in retropharyngeal abscesses." (PMID 36514104, 2022).
ROSAH syndrome (3 papers, 2022 to 2025). "We also found that untreated patients with ROSAH syndrome had frequent elevations of CRP and proinflammatory plasma cytokines including TNF and IL-6." (PMID 35868845, 2022). "Therefore, dynamic monitoring of fever and CRP levels has important clinical significance for assessing disease activity and treatment response in ROSAH syndrome." (PMID 41235249, 2025).
Senile plaques (3 papers, 2013 to 2018). Senile plaques are extracellular deposits of amyloid in the gray matter of the brain. "CRP was clearly recognized in the senile plaques (SP) from patients with AD using immunostaining, implying that the process of SP formation may include an acute-phase inflammatory state and/or the formation of CRP." (PMID 29951057, 2018). "Previous studies have demonstrated that neuronal tissue from patients with AD expresses higher amounts of CRP compared to non-AD controls and that CRP staining co-localizes with senile plaques." (PMID 29946323, 2018).
sensory impairments (3 papers, 2017 to 2025). "Moreover, elevated CRP levels were reported to be associated with the severity of clinical symptoms, cognitive and sensory impairments in SZ." (PMID 29088880, 2017).
Sensory neuropathy (3 papers, 2021 to 2022). Peripheral neuropathy affecting the sensory nerves. "Traditional serum biomarkers, such as C-reactive protein (CRP) and MPO-ANCA, cannot predict the presence and severity of peripheral motor neuropathy and sensory neuropathy in MPA." (PMID 36362162, 2022).
shigellosis (3 papers, 2019 to 2022). Shigellosis is a bacterial infection leading to dysentery and is caused by Shigella, which are small, ubiquitous Gram-negative bacteria belonging to the enterobacteria family. "The clinical presentation of case 1 was initially misinterpreted as acute bacillary dysentery due to high white blood cell count, high C-reactive protein, and normal abdomen ultrasound." (PMID 35659758, 2022). "PTX3 serum levels correlated with specific characteristics of shigellosis severity as opposed to CRP levels, which showed no such correlation, suggesting that PTX3 might be a better indicator of the colon mucosal inflammation." (PMID 35956001, 2022).
skin reaction (3 papers, 2017 to 2025). "The absence of any skin reaction at the site of injection 28 days post vaccination and lower CRP levels in IDAL sows compared to sows vaccinated with the needle-syringe show that IDAL vaccination may prevent the acute phase response and long term muscular damage associated to the injection." (PMID 28405465, 2017).
skin toxicity (3 papers, 2019 to 2020). "Recently, our lab reported that RT-induced skin toxicity was associated with an increase in plasma C-reactive protein (CRP) levels." (PMID 31138314, 2019). "In the univariate analysis, the RT field (p = 0.04) and CRP increase during the RT period (p = 0.03) were significant factors for predicting the incidence of radiation-induced skin toxicity." (PMID 31221161, 2019). "Patients with increased CRP levels were more likely to develop skin toxicity; hence, active supportive care can be applied according to CRP level changes." (PMID 31221161, 2019). "Meanwhile, RT field and C-reactive protein increase were significant factors for predicting the incidence of radiation-induced skin toxicity." (PMID 31221161, 2019).
spinal cord injury (3 papers, 2023 to 2025). Penetrating and non-penetrating injuries to the spinal cord resulting from traumatic external forces (e.g., WOUNDS, GUNSHOT; WHIPLASH INJURIES; etc.). "Erythrocyte sedimentation rate, C-reactive protein, Visual Analogue Scale score, American Spinal Cord Injury Association score, and Oswestry function index were statistically analyzed before, after postural drainage, and at the final follow-up." (PMID 40184121, 2025). "CRP concentrations have been found to be altered in subjects with spinal cord injuries." (PMID 37372810, 2023).
splenic infarct (3 papers, 2010 to 2021). "C-reactive protein was elevated in one patient showing a splenic infarct (patient No.7)." (PMID 27513466, 2016).
Ss (3 papers, 2014 to 2025). "To determine the effect of Ss infection on systemic inflammation in T2DM, we measured the levels of acute phase proteins (α-2M, CRP, haptoglobin and SAA-1) in Ss+ and Ss− individuals." (PMID 32984066, 2020). "Active TB in the presence of Ss infection exhibited significantly higher levels of α-2m, CRP, SAA and haptoglobin in comparison to NTB individuals with Ss infection." (PMID 25375117, 2014).
TAFRO syndrome (3 papers, 2019 to 2025). "While both illnesses include high levels of interleukin-6 (IL-6), TAFRO syndrome has more dramatic increases in a broader spectrum of cytokines, including vascular endothelial growth factor (VEGF) and C-reactive protein (CRP), which contribute to its aggressive clinical presentation." (PMID 39398672, 2024).
testicular germ cell tumor (3 papers, 2018 to 2025). A germ cell tumor arising from the testis. "Recent advances in the evaluation of systemic inflammatory responses using complete blood count–derived indices and C-reactive protein have opened new avenues for improving the diagnostic and prognostic assessment of testicular germ cell tumors." (PMID 41283275, 2025). "However, different studies suggested that CRP has potential as a predictive biomarker in testicular germ cell tumors (TGCTs) as it can reflect systemic inflammation linked to tumor presence and progression." (PMID 41283275, 2025).
thrombotic microangiopathy (3 papers, 2020 to 2025). The syndromes of microangiopathic hemolytic anemia, thrombocytopenia, and variable signs of organ impairment, due to platelet aggregation in the microcirculation. "Circulating biomarkers of inflammation (C-reactive protein, ferritin, and 32 cytokines), immune depression (ex vivo tumor necrosis factor response to endotoxin < 200 pg/mL), thrombotic microangiopathy (ADAMTS13 activity <57%), and EBV seropositivity (viral capsid IgG) were measured." (PMID 40828536, 2025).
transitional cell carcinoma of the bladder (3 papers, 2006 to 2024). "High preoperative CRP levels and low hemoglobin levels are independent prognostic factors linked to poor outcomes in patients undergoing radical cystectomy for urothelial carcinoma of the bladder." (PMID 39165685, 2024). "The results of the present study do not exclude nonmalignant causes of an elevated C-reactive protein in patients with transitional cell carcinoma of the urinary bladder." (PMID 17024120, 2006). "However, on multivariate analysis only C-reactive protein had independent prognostic value in patients with transitional cell carcinoma of the urinary bladder." (PMID 17024120, 2006).
tubulointerstitial nephritis (3 papers, 2021 to 2023). "In addition, CRP could be detected in the tubules of four patients with lupus-related tubulointerstitial nephritis, and the mean optical density of CRP in these patients was significantly higher than that in the normal controls (P = 0.007)." (PMID 37545739, 2023). "He had a history of intermittent fever over 38 °C with elevation of C-reactive protein (CRP) and had been diagnosed with interstitial nephritis in January 2006." (PMID 33974187, 2021).
upper tract urothelial carcinoma (3 papers, 2014 to 2023). "The combination of preoperative NLR, C-reactive protein, and plasma fibrinogen could act as an effective predictor for prognosis of patient with upper tract urothelial carcinoma." (PMID 34222026, 2021).
Ureteral obstruction (3 papers, 2021 to 2026). Obstruction of the flow of urine through the ureter. "Serum GDF-15 levels showed moderate predictive value for stone presence, and their positive correlation with inflammatory markers such as CRP supports the notion that GDF-15 may reflect both local and systemic inflammatory responses associated with ureteral obstruction." (PMID 41515626, 2026).
urethritis (3 papers, 2015 to 2023). Inflammation of the urethra. "Notably, further analysis demonstrated significant differences in PCT and CRP levels between the Urethritis and Ureteritis subgroups (PCT: Z = – 3.352, P = 0.005; CRP: Z = – 3.448, P = 0.003)." (PMID 37821527, 2023). "In our case, the patient only had a mild urethritis with no increase in white blood cell count and CRP." (PMID 25788891, 2015).
uterine fibroids (3 papers, 2022 to 2025). "CRP and D-dimer: Patients with LMS had elevated levels of C-reactive protein (CRP) and D-dimer compared with patients with uterine leiomyomas." (PMID 35884577, 2022). "Combining patients’ preoperative serum LDH, D-dimer, and CRP can be used to identify LMS and uterine leiomyomas, especially degenerative or atypical fibroids." (PMID 35884577, 2022).
viral myocarditis (3 papers, 2019 to 2024). Myocarditis that is caused by an infection with a viral agent. "The subgroup analysis of this study determined significantly higher levels of CRP among the viral myocarditis patients (8.09; 95% CI: 3.12-13.06) compared to the infective (4.01; 95% CI: 3.74-4.28) and lymphocytic myocarditis (3.90; 95% CI: 2.66-5.14)." (PMID 39564010, 2024). "Among the included studies, Qin included viral myocarditis patients with a mean age of 58.12 years which might also contribute to the higher CRP levels found among the viral myocarditis subgroup compared to the other subgroups with lower-aged participants." (PMID 39564010, 2024).
acquired hemolytic anemia (2 papers, 2023 to 2025). "Laboratory tests revealed haemolytic anaemia, increased ESR and CRP, elevated LDH, and hypocomplementemia." (PMID 41410901, 2025).
acute maxillary sinusitis (2 papers, 2006 to 2016). Acute form of maxillary sinusitis. "However, studies have found that ESR and CRP measurements have an inseparable relationship and the examination of both is useful in the diagnosis of acute maxillary sinusitis according to independent testing." (PMID 27910861, 2016).
acute pharyngitis (2 papers, 2021 to 2022). An acute and painful inflammatory process that affects the pharynx. "In her case, again, CL-O2−·, FL-OCl− and the neutrophil count increased earlier than CRP, just like the case of the 35 y/o male with acute pharyngitis." (PMID 34267248, 2021).
adenocarcinoma of the colon (2 papers, 2011 to 2024). "We report an otherwise healthy 62-year-old man with recurrent circumscribed bouts of fever and raised CRP for 3 years who has remained well and fever-free 2 years after the removal of a well-differentiated adenocarcinoma of the colon." (PMID 22567466, 2011). "Research has consistently demonstrated a correlation between high CRP and CAR levels and advanced disease stages, increased recurrence rates, and reduced survival in patients with colon adenocarcinoma." (PMID 39371828, 2024). "Inflammatory markers, such as CRP and CAR, are known to be elevated in patients with adverse clinical outcomes in colon adenocarcinoma." (PMID 39371828, 2024).
adjustment disorder (2 papers, 2022 to 2026). A category of psychiatric disorders which are characterized by emotional or behavioral symptoms that develop within 3 months of a stressor and do not persist for more than an additional 6 months after the stressor is no longer present. "Stress/adjustment disorders in models 1 and 2 were both associated with CRP with p values ​< ​0.001." (PMID 35028602, 2022). "Higher levels of systemic inflammation (CRP) were found in patients with severe stress and adjustment disorders." (PMID 41568096, 2026). "Our findings revealed several distinct immunological profiles linked to specific psychiatric conditions in youth, such as higher CRP levels in patients with severe stress and adjustment disorders." (PMID 41568096, 2026).
Adrenal insufficiency (2 papers, 2020 to 2022). Insufficient production of steroid hormones (primarily cortisol) by the adrenal glands. "Second, potential effect modifiers such as adrenal insufficiency, C-Reactive Protein (CRP), or disease severity seemed to modify the findings." (PMID 33270762, 2020). "In addition, a study that investigated the association between fever and CRP level in patients with adrenal insufficiency found a higher CRP level in febrile patients than in nonfebrile patients." (PMID 35665730, 2022).
advanced heart failure (2 papers, 2010 to 2020). Patients with advanced heart failure have severe limitations, experiences symptoms even while at rest and are mostly bedbound patients. "In general, a positive correlation between advanced heart failure and levels of the inflammatory marker C-reactive protein (CRP) has been reported." (PMID 20398245, 2010).
age-related hearing loss (2 papers, 2024 to 2025). "For instance, increased levels of C-reactive protein (CRP) and IL-6 were found in blood samples of individuals with age-related hearing loss, while a voltage-sensitive motor protein, prestin, is the main contender as a biomarker of outer hair cell damage." (PMID 41515981, 2025).
Aphasia (2 papers, 2019 to 2025). An acquired language impairment of some or all of the abilities to produce or comprehend speech and to read or write. "DELirium in Acute Ischemic Stroke (DELIAS) score = (1.272 × hemianopia) + (0.098 × aphasia) + (0.026 × age) + (0.054 × NIHSS score on admission) − (0.005 × NLR) + (0.028 × Leukocytes) + (0.001 × CRP)." (PMID 31336587, 2019). "The relationship between cardiovascular disease history, treatment window, intraoperative blood loss, thrombectomy time, neutrophil percentage, aphasia symptoms, CRP, IL-6, IL-10 and recurrence degree is not significant." (PMID 40917676, 2025).